DRD1 (dopamine receptor D1)
Diseases named in the same sentence as DRD1 in open-access papers (continued):
Sharing a sentence is not in itself a finding about the gene and the disease.
Obesity (13 papers, 2014 to 2024). Accumulation of substantial excess body fat. "In our study, ECH stimulated the browning of 3T3-L1 adipocytes via the activation of DRD1/5, suggesting that dopaminergic receptors could be an alternative target for anti-obesity drugs in the adipose tissue." (PMID 37463854, 2023). "Similar measurements associating D1-like receptor neuron activity with obesity in humans are lacking, although several animal studies found that Drd1 mRNA is reduced up to ninefold in the NAc of obese rats." (PMID 28588553, 2017). "The effectiveness of SCH23390 and quinpirole in relieving obesity and NAFLD in Trappc9-KO mice indicates that when ligands are sufficiently available, DRD1- or DRD2-containing neurons as well as their effector cells in Trappc9-KO mice function normally." (PMID 38889014, 2024). "We found that Trappc9-deficient mice presented with systemic glucose homeostatic disturbance, obesity, and NAFLD, which were relieved upon chronic treatment combining dopamine receptor D2 (DRD2) agonist quinpirole and DRD1 antagonist SCH23390." (PMID 38889014, 2024). "As the treatment combining DRD1 antagonist SCH23390 and DRD2 agonist quinpirole is effective in ameliorating deficits associated with multiple behaviors in Trappc9-KO mice, we reasoned that this treatment might also be beneficial in controlling obesity or NAFLD in Trappc9-KO mice." (PMID 38889014, 2024). "Recent data that we published showed a decrease in DRD4 and DRD1 expression with the onset of insulin resistance, while DRD2 expression remained unchanged with the progression of metabolic dysregulation in obesity." (PMID 36768789, 2023). "Taken together, our findings suggest that dopamine receptor D1- and D2-agonists might not constitute a promising therapeutic approach for peripherally inducing BAT thermogenesis for treatment of obesity or associated metabolic disorders." (PMID 33214601, 2020). "Overall, our findings show that the thermogenic action of ECH via the activation of DRD1 and DRD5 significantly contributed to beiging and ATP-consuming futile cycles that dissipate energy, which may be beneficial in the development of innovative approaches to obesity treatment." (PMID 37463854, 2023).
Alzheimer disease (9 papers, 2013 to 2025). A progressive, neurodegenerative disease characterized by loss of function and death of nerve cells in several areas of the brain leading to loss of cognitive function such as memory and language. "DRD1, and the dopaminergic system in general, has also been implicated in Alzheimer’s disease." (PMID 38045237, 2023). "GHSR1a enhances DRD1-induced initiation of hippocampal synaptic plasticity and formation of hippocampal memory, and these complexes are disrupted in Alzheimer’s disease." (PMID 36943057, 2023). "Recently, a reduction in GHSR1a-DRD1 complexes in favour of establishment of GHSR1a-Aβ complexes was shown to correlate with Alzheimer’s disease." (PMID 34663757, 2021). "Targeting GHSR1a-DRD1 heteromers with a bitopic agonist could be an important preventative treatment for Alzheimer’s disease, although the effects on food intake and insulin secretion would need to be assessed carefully." (PMID 36943057, 2023). "The ability to rescue these complexes in hippocampal tissue, with consequent prolonged functionality, indicates that co-stimulation of GHSR1a-DRD1 could be an important preventative treatment for Alzheimer’s disease." (PMID 34663757, 2021). "Additionally, a reduction in GHSR1a-DRD1 complexes in favour of establishment of GHSR1a-Aβ complexes correlates with Alzheimer’s disease, indicating that GHSR1a heteromers may have pathological functions." (PMID 34663757, 2021).
nicotine addiction (8 papers, 2014 to 2023). "Epidemiological investigations have revealed correlations between nicotine-induced addiction and five single nucleotide polymorphisms in the DRD1 gene, suggesting that DRD1 mediates nicotine addiction." (PMID 37047614, 2023). "It has been known that DRD1 is associated with nicotine dependence, and miR-504 up-regulates DRD1 expression by targeting the DRD1 3′ UTR38." (PMID 31434869, 2019). "In addition, an epidemiologic study revealed that the DRD1 gene is correlated with nicotine addiction by investigating the relationship between five single-nucleotide polymorphisms within or near the DRD1 gene and nicotine addiction." (PMID 33804804, 2021). "miR-133b negatively regulates the expression of transcription factor, Pitx3, which activates the dopamine receptor (DRD1), a mediator of nicotine addiction in smokers." (PMID 24479666, 2014). "It has been proven that miR-504 increases the expression of the dopamine D1 receptor gene (DRD1), which is related to nicotine dependence." (PMID 34503246, 2021). "In the network of genes annotated to the cocaine pathway (also in the nicotine addiction pathway), ADCY5, DRD1, DRD2, PPP1R1B, and protein kinase C β (PRKCB) were over-expressed in Control nursed males relative to all pig groups with exception of Control weaned females." (PMID 35627199, 2022).
attention deficit-hyperactivity disorder (7 papers, 2005 to 2023). A disorder characterized by a marked pattern of inattention and/or hyperactivity-impulsivity that is inconsistent with developmental level and clearly interferes with functioning in at least two settings (e.g. at home and at school). "In addition, DRD1 variation seems to be associated with behaviours involving a degree of impulsivity, such as attention deficit hyperactivity disorder (ADHD) in children, and gambling in adults." (PMID 30393594, 2018).
cocaine addiction (7 papers, 2012 to 2024). "Dat contains an association between DRD1 and cocaine related disorders, with multiple clinical trials being undertaken to analyse the use of Propranolol as a treatment for cocaine addiction as well as cocaine cravings (Medical University of South Carolina, 2015)." (PMID 26844016, 2016). "We observed the activation of the Drd1 and Drd2 genes, coding for dopamine receptor 1 and 2 of the dopaminergic synapse, which are also key elements of the cocaine addiction- and alcoholism-related pathways." (PMID 36981011, 2023). "Further analysis on dataset of cocaine-addicted mice revealed that Drd1 and Drd2 genes are both upregulated in cocaine addiction and are almost solely expressed in excitatory neurons, with Drd1 also being found at lower levels in inhibitory neurons, oligodendrocyte and endothelial cells in the mPFC." (PMID 34712123, 2021). "Although the functional role of each subtype remains to be investigated, this suggests that certain Drd1-expressing neuronal subtypes in the PFC may be more involved in the process of cocaine addiction than others." (PMID 34712123, 2021). "Concerning the known dopamine receptors, it has been reported that DRD1 and DRD2 are the most involved in cocaine addiction, whereas DRD3 and DRD4 are less relevant in the addiction process." (PMID 23285158, 2012).
hepatocellular carcinoma (7 papers, 2021 to 2026). A malignant tumor that arises from hepatocytes. "DRD1 is highly expressed in hepatocellular carcinoma tissue, and high expression of DRD1 is associated with poor prognosis in liver cancer patients." (PMID 38494840, 2024). "For instance, upregulation of DA and DA receptor D1 (DRD1) has been associated with tumor growth and invasion of hepatocellular carcinoma (HCC)." (PMID 35954387, 2022). "DRD1 signaling promoted hepatocellular carcinoma (HCC) cell growth." (PMID 37215113, 2023). "Notably, gene hubs like Drd1, Gria1‐4, Grin1, Grin2b, Grm5, and GABAα receptor genes were also highly connected, mirroring gene expression patterns observed in liver fibrosis, cirrhosis, and hepatocellular carcinoma (HCC)." (PMID 41508419, 2026).
Huntington disease (7 papers, 2013 to 2026). Huntington disease (HD) is a rare neurodegenerative disorder of the central nervous system characterized by unwanted choreatic movements, behavioral and psychiatric disturbances and dementia. "The progression of Huntington’s Disease (HD) predominantly impacts spiny projection neurons (SPNs) in the striatum, with Drd2-expressing iSPNs being particularly susceptible compared to Drd1-expressing dSPNs." (PMID 38918688, 2024). "Networks associated with the most frequent temporal subtypes of molecular responses in the Drd1-expressing neurons of Huntington’s disease (HD) knock-in model mice." (PMID 33618800, 2021). "The DNA polymerase Chtf18 (up-regulation assigned to Drd1-MSNs: pathogenic response that is aggravated then maintained) may be involved in DNA repair, a process genetically associated with human HD onset age (Genetic Modifiers of Huntington’s Disease (GeM-HD) Consortium, 2019)." (PMID 33618800, 2021).
alcohol dependence (6 papers, 2014 to 2023). Physical and psychological dependence on alcohol. "Alcohol dependence was significantly, more precisely associated with a specific haplotype rs686*T-rs4532*G within the DRD1 gene." (PMID 24878765, 2014). "In addition, in humans, an autoradiographic clinical study found a 23% reduction in DRD1 affinity in the NAc region among individuals with type I alcohol dependence and a 14% reduction in DRD1 association among individuals with type II alcohol dependence." (PMID 37049542, 2023). "Effects of alcoholism on the whole tissue levels of PDYN, OPRK1, DRD1, and DRD2 mRNAs in NAc were examined after adjusting for demographical data and tissue characteristics including age, PMI, brain pH, and RQI." (PMID 29383684, 2018). "First, we examined whether DRD1 and DRD2 expression is affected by alcoholism, and whether alcoholism effects may be due to neuronal proportion in the alcoholic brain." (PMID 29383684, 2018). "Importantly, observed downregulation of DRD1 expression but unaltered KOR and DRD2 mRNA in alcoholics corroborates our previously demonstrated decline in D1-receptor as well as unchanged D2- and KOR receptor-binding potential in NAc of human alcoholics and in rat model of alcohol dependence." (PMID 29383684, 2018).
autism (6 papers, 2012 to 2025). Persistent deficits in social interaction and communication and interaction as well as a markedly restricted repertoire of activity and interest as well as repetitive patterns of behavior. "Collectively, these results indicated that enhanced activity of DRD1-MSNs in the left striatum is responsible for autism-like behaviors in Sh3rf2 deletion mice." (PMID 40890295, 2025). "Subsequently, we investigated whether the heightened activity of DRD1-MSNs in the left striatum contributes to autism-like behaviors in Sh3rf2 KO mice." (PMID 40890295, 2025). "Following our findings with the DRD1 gene, and as part of our investigation to determine whether other DA-related genes are significant factors in the etiology of ASDs, we found evidence for association of the DRD2 and PPP1R1B genes with autism in affected males from multiple-incidence families." (PMID 22559203, 2012).
memory impairment (6 papers, 2020 to 2025). "These include both serious ADRs (heart failure for ADRA2B, DRD1, and DRD2 activation) and lower severity effects (sleep or memory impairments for several targets)." (PMID 37468498, 2023).
mood disorder (6 papers, 2014 to 2025). A cognitive disorder a disturbance in which the person's mood is hypothesized to be the main underlying feature. "In the cluster, particular attention was given to investigating the risk posed by dopamine receptors genes (i.e., DRD1, DRD2, DRD3, and DRD4) in the development of mood disorders." (PMID 36833279, 2023). "In addition to SHANK3, miR-504 also regulates the expression of the dopamine D1 receptor gene (DRD1), expression or activity of which is associated with multiple neuropsychiatric disorders including mood disorders." (PMID 26572867, 2015). "Changes in Drd1 mRNA levels have been previously documented in the DLPFC of individuals affected by SCZ and mood disorders." (PMID 40558531, 2025).
psychosis (6 papers, 2014 to 2024). "DRD1 genetic variation and gene expression in different brain regions has been implicated with aggression, cognitive impulsivity, and psychosis." (PMID 38167211, 2024). "A genetic association was found in the gene coding for DRD1 with psychosis and aggression in Alzheimer patients." (PMID 24691403, 2014). "In contrast, DRD1 and 5HTR2C were DEGs for the psychosis and agitation domains while the psychosis domain also demonstrated DRD2 and DRD4 as DEGs." (PMID 38575567, 2024).
epilepsy (5 papers, 2013 to 2024). A brain disorder characterized by episodes of abnormally increased neuronal discharge resulting in transient episodes of sensory or motor neurological dysfunction, or psychic dysfunction. "Interestingly, glycine receptor alpha 3 (Glra3) and dopamine receptor D1 (Drd1) were genes involved in more than two annotations related to epilepsy." (PMID 38338984, 2024). "At several epilepsy-related genes, like HDAC11, SPP1, GAL, DRD1 and SV2C, significant differential methylation and differential gene expression coincided." (PMID 31887157, 2019).
glioblastoma (5 papers, 2020 to 2024). The most malignant astrocytic tumor (WHO grade IV). "Research on glioblastoma has shown that DRD1 expression is closely and positively associated with a favourable clinical prognosis." (PMID 34717619, 2021). "In glioblastoma (GBM), DRD1 expression is associated with a more favorable prognosis, and one study found that DRD1 agonism inhibited cell growth through disrupting autophagic flux and showed that the DRD1 agonist SKF83959 and the chemotherapeutic temozolomide have a synergistic antitumor effect." (PMID 38572507, 2024). "Knockdown of nine PTGs significantly decreased cell viability, of which lower expression levels of DRD1, DRD2, HTR3A and TACR1 were also associated with better patient survival in The Cancer Genome Atlas (TCGA) glioblastoma cohort." (PMID 39304781, 2024). "The activation of DRD1 was reported to inhibit the growth of glioblastoma, and in the same study, tumor cells with a high DRD1 level were more sensitive to dopamine than those with a low level." (PMID 34031366, 2021). "In addition, DRD1 activation attenuated glioblastoma cell malignant activities through the mediation of autophagic activity." (PMID 34717619, 2021). "In glioblastoma, researchers observed that DRD1 was decreased in tumour tissues." (PMID 34717619, 2021). "In addition, DRD1 activation was validated to suppress glioblastoma tumour cell progression." (PMID 34717619, 2021). "Dopamine and dopamine receptor D1 (DRD1), a key member of the dopamine receptor family, exert positive effects on lung cancer, pancreatic cancer, and glioblastoma." (PMID 34717619, 2021).
heart failure (5 papers, 2016 to 2023). Inability of the heart to pump blood at an adequate rate to meet tissue metabolic requirements. "Expressions of Drd1 were identified in a limited number of CMs of sham-operated mice, and the number of Drd1-expressing CMs was increased during the progression of heart failure induced by pressure overload." (PMID 32868781, 2020). "To examine the roles of cardiac D1R in the pathophysiology of heart failure, we generated mice with CM-specific deletion of Drd1 gene by crossing αMHC-Cre mice with Drd1flox/flox mice (αMHC-Cre/Drd1fl/fl)." (PMID 32868781, 2020). "Moreover, the expression of Drd1 was strongly related with that of Nppa and Nppb, which are well-established markers of cardiac hypertrophy and heart failure." (PMID 32868781, 2020).
liver fibrosis (5 papers, 2020 to 2026). "In addition, recent findings have demonstrated the advantages of suppressing YAP/TAZ in fibroblasts by activating the dopamine receptor D1 (DRD1) in mouse models of lung and liver fibrosis." (PMID 36926329, 2023). "Although further studies in the human liver are needed, targeting YAP/TAZ via DRD1 could prove a useful pharmacological and cell-selective approach to reverse liver fibrosis." (PMID 34938271, 2021). "DRD1 stimulation selectively inhibited cellular YAP/TAZ function, shifted the cell phenotype from profibrotic to fibrosis resolving, and ameliorated liver fibrosis in mice." (PMID 34938271, 2021).
lung carcinoma (5 papers, 2020 to 2025). "One of the key phenotypes we consistently observed following loss of DRD1 expression in lung cancer cells is increased cell proliferation." (PMID 38572507, 2024). "An interesting study in an American population found that rs686 polymorphism in DRD1 increased the risk of lung cancer in those who were exposed to second-hand smoke during childhood." (PMID 33287325, 2020). "Our previous work showed that DRD1 is a lung cancer susceptibility gene." (PMID 38572507, 2024). "DRD1 specifically is downregulated in lung cancer, at least partially through methylation of the DRD1 promoter." (PMID 38572507, 2024). "Treatment of lung cancer cells with the demethylation agent 5′AZA increased mRNA expression of DRD1, further supporting the epigenetic regulation of DRD1 expression in lung cancer (data not shown)." (PMID 38572507, 2024). "CRISPR‐mediated knockout of DRD1 in lung cancer cell lines significantly increases cell proliferation, as does shRNA‐mediated stable DRD1 knockdown." (PMID 38572507, 2024). "We recently demonstrated a link between a SNP in dopamine receptor D1 (DRD1) and risk of lung cancer." (PMID 38572507, 2024). "The present study is the first to describe the antiproliferative effects of DRD1 in lung cancer, as well as its mechanism." (PMID 38572507, 2024). "To understand the molecular mechanisms linking DRD1 with lung cancer, we generated stable cell lines harboring CRISPR‐mediated knockout of DRD1, shRNA‐mediated stable DRD1 knockdown, or stable induced overexpression of V5‐tagged DRD1." (PMID 38572507, 2024). "Combined, these data suggest that DRD1 gene methylation controls DRD1 expression in lung cancer and that aberrant DRD1 methylation is an early event in lung tumorigenesis." (PMID 38572507, 2024). "In lung cancer cells, DRD1 signaling reduces proliferation through reduced EGFR signaling, and it also reduces PD‐L1 expression." (PMID 38572507, 2024). "We found DRD1 mRNA expression significantly downregulated by ~80% in human lung cancer tissues as compared with non‐involved tissues." (PMID 38572507, 2024). "The current study is limited in that the reported alterations of PD‐L1 expression following DRD1 modulation were only observed in vitro using cultured lung cancer cell lines." (PMID 38572507, 2024). "Here, we show that DRD1 signaling has several anticancer functions that may be targetable in lung cancer patients." (PMID 38572507, 2024). "We did, however, observe that DRD1 regulates PD‐L1 expression in multiple lung cancer cell lines." (PMID 38572507, 2024). "Utilizing preinvasive CIS tissue, we also show that aberrant hypermethylation of the DRD1 promoter is an early event in lung cancer, which may be predictive of disease progression in lung CIS patients." (PMID 38572507, 2024). "Indeed, we found that the DRD1 promoter is significantly hypermethylated in lung cancer using samples from the NCI‐MD cohort and then validated this observation using squamous cell carcinoma and adenocarcinoma data from TCGA." (PMID 38572507, 2024). "The present study demonstrates that DRD1 exerts a tumor suppressive‐like role in lung cancer cells via modulation of EGFR signaling and cell proliferation and that the dopamine network regulates the expression of the immune checkpoint molecule, programmed death‐ligand 1 (PD‐L1)." (PMID 38572507, 2024). "Interestingly, we also found that DRD1 regulates the expression of PD‐L1 in lung cancer cells." (PMID 38572507, 2024). "Therefore, to investigate the hypothesis that DRD1 is directly involved in lung cancer, we measured DRD1 mRNA expression in both human lung cancer tissues and paired non‐involved tissues in samples from the NCI‐MD case control study using RT‐PCR." (PMID 38572507, 2024). "Together, our data suggest that DRD1 can reduce the phosphorylation and total expression of EGFR protein in lung cancer cells." (PMID 38572507, 2024).